CAPN1 (calpain 1)
Description:
Calcium-regulated non-lysosomal thiol-protease which catalyzes limited proteolysis of substrates involved in cytoskeletal remodeling and signal transduction. Proteolytically cleaves CTBP1 at 'Asn-375', 'Gly-387' and 'His-409'. Cleaves and activates caspase-7 (CASP7).
Synonyms: muCANP; CANPL1; muCL; CANP; CANP1; SPG76
Tractability: Small molecule: a structure with a bound ligand is known; a high-quality ligand is known; it has a high-quality binding pocket; it belongs to a druggable protein family. Antibody: UniProt places it where antibodies can reach, with high confidence; its Gene Ontology location is reachable by antibodies, with high confidence. PROTAC: ubiquitination databases record sites on it; its protein half-life has been measured; a small molecule that binds it is known.
Target class: Protease; Enzyme; Cysteine protease C2 family; Cysteine protease CA clan; Cysteine protease
Chemical probes: CHEMBL69715
Gene: Protein-coding gene on chromosome 11 (65,180,566 to 65,212,006, forward strand). Ensembl gene ENSG00000014216.
Subcellular location: Cytoplasm; Cell membrane
Subcellular location (Human Protein Atlas): Cytosol
Pathways (Reactome):
Developmental Biology: Formation of the cornified envelope
Disease: Deregulated CDK5 triggers multiple neurodegenerative pathways in Alzheimer's disease models
Extracellular matrix organization: Degradation of the extracellular matrix
Immune System: Neutrophil degranulation
Gene Ontology:
Molecular function: calcium ion binding; calcium-dependent cysteine-type endopeptidase activity; peptidase activity; protein binding
Biological process: proteolysis; regulation of catalytic activity; self proteolysis; NMDA selective glutamate receptor signaling pathway; positive regulation of cell population proliferation; regulation of macroautophagy
Cellular component: cytoplasm; cytosol; extracellular exosome; focal adhesion; membrane; plasma membrane; extracellular region; ficolin-1-rich granule lumen; cornified envelope; lysosome; mitochondrion
Genetic constraint (gnomAD): Loss-of-function variants: 73 observed, 90.82 expected, observed/expected ratio (o/e) 0.8, 90% interval 0.67 to 0.98. The upper end of that interval is the gene's LOEUF score, 0.98, which puts it in group 4 of 6, group 1 being the genes least tolerant of losing a copy. Missense variants: 827 observed, 963.51 expected, observed/expected ratio (o/e) 0.86, 90% interval 0.81 to 0.91. Synonymous variants: 354 observed, 384.73 expected, observed/expected ratio (o/e) 0.92, 90% interval 0.84 to 1.
Homologues: Orthologues: macaque CAPN1 (98% identical), dog CAPN1 (97% identical), chimpanzee CAPN1 (96% identical), pig CAPN1 (95% identical), guinea pig CAPN1 (94% identical), mouse Capn1 (89% identical), rat Capn1 (88% identical), rabbit CAPN1 (88% identical), tropical clawed frog capn1 (77% identical), zebrafish capn1 (69% identical), zebrafish CAPN1 (66% identical), Caenorhabditis elegans clp-1 (35% identical), and 7 more. Paralogues in human: CAPN2 (62% identical), CAPN8 (58% identical), CAPN3 (53% identical), CAPN11 (53% identical), CAPN9 (52% identical), CAPN12 (43% identical), CAPN14 (36% identical), CAPN13 (32% identical), CAPN5 (29% identical), CAPN6 (26% identical), CAPN10 (24% identical), CAPN7 (24% identical), and 8 more.
Diseases named in the same sentence as CAPN1 in open-access papers:
CAPN1 is named in the same sentence as 156 diseases in open-access papers, as found by Europe PMC text mining. Sharing a sentence is not in itself a finding about the gene and the disease. The quoted sentences say what the papers report.
Ataxia (26 papers, 2013 to 2025). Ataxia refers to impaired coordination of voluntary muscle movement. "The neuroprotective properties of calpain-1 were also further supported by studies in mice, dogs, and humans with null mutations or deletions of calpain-1, which result in cerebellar ataxia." (PMID 40940713, 2025). "Human mutations in the calpain 1 gene (CAPN1) have been associated with cerebellar ataxia, hereditary spastic paraplegia, and spinal muscular atrophy." (PMID 39195282, 2024). "Since then, a number of families with mutations in calpain-1 have been identified and they all exhibit spinocerebellar ataxia and cognitive impairments." (PMID 38361744, 2024). "It had also been reported by the Russel Terrier dog, which presents with a null mutation of calpain-1, also exhibits cerebellar ataxia." (PMID 38361744, 2024). "We were contacted by a British neurologist, Dr. Holden, who was following a patient with a null mutation of calpain-1 and who exhibited severe cerebellar ataxia." (PMID 38361744, 2024). "The KCNJ10 c.627C>G variant, or rarely the CAPN1 c.344G>A variant, was confirmed to be the causal variant of spinocerebellar ataxia." (PMID 37905444, 2023). "One Parson Russell terrier with spinocerebellar ataxia alone was biallelic for the CAPN1 c.344G>A variant." (PMID 37905444, 2023). "Variants in KCNJ10 are widely reported to explain spinocerebellar ataxia in affected dogs, a variant in another gene, CAPN1 (c.344G>A), is reported in Parson Russell terriers presenting with spinocerebellar ataxia without myokymia, neuromyotonia or epilepsy." (PMID 37905444, 2023). "This study aims to clarify the potential association between variants in KCNJ10 and CAPN1 genes and myokymia and neuromyotonia in a cohort of 33 dogs with spinocerebellar ataxia, myokymia/neuromyotonia, or both." (PMID 37905444, 2023). "Mutations in CAPN1 (calpain-1) have been associated with SPG76, spastic paraplegia accompanied with ataxia and spastic ataxia." (PMID 33917666, 2021). "CAPN1 loss-of-function variants lead to autosomal recessive spastic paraplegia-76 in human patients and spinocerebellar ataxia in Parson Russell Terriers." (PMID 34946872, 2021). "The antiapoptotic role of SMN and the activation of apoptotic processes through the PI3K-Akt neuronal survival pathway has been stablished in SMA and has been associated with CAPN1 loss of function in cerebellar ataxia." (PMID 35126465, 2021). "In this regard, previously identified CAPN1 mutations are a known genetic cause for cerebellar ataxia and hereditary spastic paraplegia (HSP)." (PMID 35126465, 2021). "Mutations in CAPN1 have been previously associated with cerebellar ataxia and hereditary spastic paraplegia." (PMID 35126465, 2021). "By reviewing the clinical manifestations of SPG76 patients, we validated the “spastic-ataxia” phenotype and emphasized the association between spasticity and ataxia, indicating the importance of CAPN1 screening in HSP patients." (PMID 31023339, 2019). "Mutations in CAPN1 have recently been identified in a complicated form of Hereditary Spastic Paraplegia (HSP) with a combination of cerebellar ataxia and corticomotor tract disorder (SPG76)." (PMID 31231303, 2019). "Further, a missense mutation in CAPN1 is associated with spino-cerebellar ataxia in the Parson Russell terrier dog breed and has recently been reported in humans with cerebellar ataxia and limb spasticity." (PMID 30148849, 2018). "This dog carried two copies of the recessive spinocerebellar ataxia (CAPN1 gene) mutation originally identified in Parson Russell and Jack Russell Terriers." (PMID 29708978, 2018). "A missense mutation in the CAPN1 gene (c.344G > A) was associated with a late-onset spinocerebellar ataxia phenotype (LOA) in a cohort of PRT." (PMID 27724896, 2016). "KCNJ10 and CAPN1 variants cause “spinocerebellar” ataxia in dogs, but their association with generalized myokymia and neuromyotonia remains unclear." (PMID 37905444, 2023).
Ataxia (continued). "The KCNJ10 c.627C>G variant was confirmed to be the causal variant in nearly all affected dogs with clinical signs of spinocerebellar ataxia, except for 1 dog in which the CAPN1 variant was detected and another dog for which the diagnosis remains unknown." (PMID 37905444, 2023). "Calpain-1 deficiency in mice and humans (due to CAPN1 mutation) helped bring about ataxia." (PMID 36268783, 2022). "In addition, CAPN1 mutations have been reported to induce cerebellar ataxia in some human families and missense mutations in calpain-1 have been found to cause spinocerebellar ataxia in dogs." (PMID 35432334, 2022). "Interestingly, several human families carrying CAPN1 mutations were found to exhibit cerebellar ataxia and Russell terrier dogs carrying a missense mutation in calpain-1 also exhibit spinocerebellar ataxia." (PMID 33339205, 2020). "The finding represents the first association of a mutation in CAPN1 with spinocerebellar ataxia and may represent a novel candidate gene for ataxia in human patients." (PMID 23741357, 2013). "We carefully analyzed the gait properties of our calpain-1 ko mice and found that they also exhibited cerebellar ataxia." (PMID 38361744, 2024). "This circumstance is highlighted by mutations in the human CAPN1 gene, which reportedly cause spastic paraplegia 76 (SPG76) or a form of cerebellar ataxia." (PMID 36385755, 2022). "Loss-of-function mutations in CAPN1 are known to cause cerebellar ataxia and hereditary spastic paraplegia (HSP) with the number of ataxia and/or pure HSP patients reporting CAPN1 mutations rapidly increasing." (PMID 35126465, 2021). "The large decrease in the expression of genes and proteins in this pathway fits well with the neuroprotective function of calpain-1 in the brain and the recent findings that humans with calpain-1 deletion exhibit a variety of forms of ataxia/spasticity." (PMID 32328086, 2020). "CAPN1 gene was identified as an AR-HSP pathogenic gene in 2016 and the patients presented complex HSP, including peripheral neuropathy, ataxia, ocular movement abnormalities, dysarthria (SPG76)." (PMID 31289639, 2019). "Recently, the missense mutation KCNJ10:c.627C > G was shown to be associated with the spinocerebellar ataxia (SCA) in JRT and related Russell group of terriers, whereas the missense mutation CAPN1:c.344G > A was associated with late onset ataxia (LOA) in PRT." (PMID 27724896, 2016). "Given the functional implications and high level of conservation observed across species, the CAPN1 variant represents a provocative candidate for the cause of SCA in the PRT and a novel potential cause of ataxia in humans." (PMID 23741357, 2013). "A previous study that used GWAS and targeted resequencing to investigate a different form of canine cerebellar ataxia in Russell Terrier Group dogs identified a variant in CAPN1, which had also not previously been implicated in ataxia in humans." (PMID 31999692, 2020). "Among these patients carrying CAPN1 mutations, lower limbs spasticity was the predominant symptom combined with cerebellar ataxia or not." (PMID 31023339, 2019). "Calpain-1 deletion elicits neurodevelopmental disorders, such as ataxia." (PMID 29152136, 2017). "In addition, dogs presenting only with myokymia or neuromyotonia (without ataxia) did not carry the reported KCNJ10 or CAPN1 variants (4 dogs)." (PMID 37905444, 2023). "Mutations in CAPN1 have not previously been associated with ataxia in any species." (PMID 23741357, 2013). "Similarly, mutations in CAPN1 cause HSP with or without ataxia." (PMID 33646413, 2021). "All these observations indicated that CAPN1 screening is necessary in HSP patients, especially when patients suffer from spasticity-ataxia phenotype." (PMID 31023339, 2019). "The only Parson Russell terrier, also suffering from spinocerebellar ataxia, did not carry this KCNJ10 variant, but was biallelic for the CAPN1 c.344G>A variant." (PMID 37905444, 2023).
Ataxia (continued). "Together with previously reported cases, our study broadened the clinical and molecular spectrum of CAPN1-related SPG76 and exemplified the concept of “spasticity-ataxia” phenotype, further increasing our understanding of complicated HSP form and its connection with cerebellar ataxia." (PMID 31023339, 2019).
breast cancer (13 papers, 2012 to 2025). A primary or metastatic malignant neoplasm involving the breast. "Specifically, recent literature has highlighted the significant association of CAPN1 with breast cancer and particularly TNBC." (PMID 40744683, 2025). "We have previously shown that high calpain-2 expression is associated with worse prognosis in patients with basal-like or triple-negative diseases and that calpain-1 expression is associated with trastuzumab response in HER2+ breast cancer patients." (PMID 27798717, 2017). "Significant association was also found between high caspase-3/high calpain-1 and breast cancer-specific survival in the total patient cohort (P = 0.005) and basal-like subgroup (P = 0.034), as indicated by Kaplan–Meier analysis." (PMID 27798717, 2017). "Low calpastatin expression was significantly associated with adverse breast cancer-specific survival of the inflammatory breast cancer patients (P=0.020), as was low calpain-1 expression (P=0.003)." (PMID 27323818, 2016). "In inflammatory cases, high calpain-1 and high calpastatin expression is associated with improved breast cancer-specific survival." (PMID 27323818, 2016). "In breast cancer high calpain-1 and calpain-2 expression has been associated with adverse clinical outcome." (PMID 25539577, 2014). "High calpain-2 expression in breast cancer is associated with poor survival in patients with triple negative or basal-like phenotype tumours; and high expression of calpain-1 can predict response following adjuvant trastuzumab therapy." (PMID 25539577, 2014). "An interesting observation of this study is that low calpain-9 expression is associated with disease-specific survival, whereas high expression of calpain-1 and calpain-2 are associated with poor breast cancer prognosis in other studies." (PMID 25539577, 2014). "Notably, CAPN1 has been extensively investigated in previous literature and is suggested to be potentially associated with the incidence and prognosis of breast cancer." (PMID 40744683, 2025). "High caspase-3/high calpain-1, high caspase-3/high calpain-2 and high caspase-3/low calpastatin expression significantly associated with adverse breast cancer-specific survival in the total patient cohort; and combinational caspase-3/calpain-1 has important prognostic value in basal-like patients." (PMID 27798717, 2017). "In subgroup analyses, a significant association was found between caspase-3/calpain-1 and breast cancer-specific survival in the basal-like subgroup (P = 0.034), the same pattern shown in the total group (high caspase-3/high calpain-1) that was associated with poor prognosis." (PMID 27798717, 2017). "The aim of this study was to investigate the expression of calpain-1, calpain-2 and calpastatin in diagnostic, core biopsy specimens from women with large but operable primary breast cancer who were subsequently treated with neoadjuvant chemotherapy prior to surgical excision of residual tumour." (PMID 27323818, 2016). "Furthermore, low expression of calpastatin and calpain-1 is significantly associated with adverse breast cancer-specific survival in inflammatory large but operable primary breast cancer." (PMID 27323818, 2016). "Furthermore, low calpain-1 and calpastatin expression are associated with adverse survival of patients with inflammatory large but operable breast cancer." (PMID 27323818, 2016). "The expression levels of these proteins have previously been investigated in breast cancer, with results indicating that expression of calpain-1 is associated with relapse-free survival in HER2 positive breast cancer patients treated with trastuzumab following adjuvant chemotherapy." (PMID 22435971, 2012). "Thus, we sought to determine whether loss of calpain-1/2 in a HER2+ tumor cell line model might cooperate with therapeutic challenge from these two commonly used treatments of breast cancer." (PMID 30279968, 2018).
breast cancer (continued). "The expression of calpain-1, calpain-2 and calpastatin was determined in diagnostic core biopsy samples taken from patients with large but operable breast cancer or locally advanced breast cancer who subsequently received neoadjuvant chemotherapy prior to surgical resection." (PMID 27323818, 2016). "This complexity underscores the need for further research to elucidate CAPN1's intricate role in breast cancer pathology and clarify its implications for future treatment strategies." (PMID 40744683, 2025). "Expression of the calcium-activated protease isoforms calpain-1 and calpain-2 has been correlated with cell migration and invasion in vitro, metastatic potential in preclinical mouse models of cancer, and breast cancer prognosis in patients." (PMID 40940726, 2025). "High calpain-1 protein levels correlated with poor relapse-free survival of HER2+ breast cancer patients treated with trastuzumab following adjuvant chemotherapy." (PMID 37795261, 2023). "In that sense, early studies showed that calpain-1 is differentially expressed in the peritumoural and intratumoral area of breast cancer patients." (PMID 37795261, 2023). "Induced apoptosis in MCF-7 or MD-468 breast cancer cells was shown to be mediated by calpain-1 translocation into the nucleus." (PMID 37795261, 2023). "Our previous work has shown that the ubiquitously expressed calpain-1 and -2 isoforms regulate cell survival in response to cytotoxic challenges and promote breast cancer cell line resistance to chemotherapeutics including doxorubicin and cisplatin." (PMID 30279968, 2018). "Translational studies have revealed that high calpain-2 expression correlates with adverse outcomes in basal-like or triple-negative breast cancer, while high calpain-1 expression correlated with poor relapse-free survival in HER2+ breast cancer." (PMID 30279968, 2018). "Of specific relevance to this study, CAPN1 expression in HER2+ breast cancer has been positively correlated with shorter relapse-free survival and resistance to trastuzumab." (PMID 30279968, 2018). "The calpain system in general has been implicated in tumour progression, including altering cellular migration, survival and apoptosis; and expression of calpain-1, calpain-2 and calpastatin have been shown to be important in breast cancer." (PMID 25539577, 2014). "Aberrant expression of calpain family members has been implicated in tumour progression in a number of cancers and expression of calpain-1 and calpain-2 in breast cancer has been shown to be important in patient prognosis." (PMID 25539577, 2014). "Our research specifically focused on examining the expression of CAPN1 in breast cancer." (PMID 40744683, 2025). "While high calpain-2 and low CAST expression was associated with improved survival in patients with non-inflammatory breast cancer treated with neoadjuvant chemotherapy, high calpain-1 and high CAST expression in the inflammatory group was associated with improved breast cancer survival." (PMID 37795261, 2023). "The pro-tumoral environment might trigger the molecular switch from the physiological calpain-2/E-cadherin to the metastatic calpain-1/E-cadherin-cleavage observed in breast cancer cell lines." (PMID 37795261, 2023). "Hence, targeting calpain-1 and calpain-2 was proposed as a novel therapeutic strategy for mammary tumors." (PMID 37795261, 2023). "This review considers these standpoints to cover the paradoxical role of calpain-1 and -2 in the mammary tissue either, under the physiological conditions of the postlactational mammary gland regression or the pathological context of breast cancer." (PMID 37795261, 2023). "Collectively, these results indicate pro-tumorigenic roles for calpains-1/2 in HER2+ breast cancer and provide evidence that calpain-1/2 inhibitors could have anti-tumor effects if used either alone or in combination with chemotherapeutics and targeted agents." (PMID 30279968, 2018).